RPRD1A (regulation of nuclear pre-mRNA domain containing 1A)
Description:
Interacts with phosphorylated C-terminal heptapeptide repeat domain (CTD) of the largest RNA polymerase II subunit POLR2A, and participates in dephosphorylation of the CTD by RPAP2. May act as a negative regulator of cyclin-D1 (CCND1) and cyclin-E (CCNE1) in the cell cycle.
Synonyms: P15RS; FLJ10656; HsT3101
Tractability: PROTAC: ubiquitination databases record sites on it; its protein half-life has been measured.
Gene: Protein-coding gene on chromosome 18 (35,984,387 to 36,067,576, reverse strand). Ensembl gene ENSG00000141425.
Subcellular location: Nucleus
Subcellular location (Human Protein Atlas): Golgi apparatus; Nucleoplasm
Pathways (Reactome):
Gene expression (Transcription): RNA polymerase II transcribes snRNA genes
Gene Ontology:
Molecular function: protein binding; RNA polymerase II complex binding; identical protein binding; RNA polymerase II C-terminal domain binding
Biological process: RNA polymerase II promoter clearance; mRNA 3'-end processing
Cellular component: nucleoplasm; nucleus; transcription preinitiation complex
Genetic constraint (gnomAD): Loss-of-function variants: 7 observed, 29.9 expected, observed/expected ratio (o/e) 0.23, 90% interval 0.13 to 0.44. The upper end of that interval is the gene's LOEUF score, 0.44, which puts it in group 1 of 6, group 1 being the genes least tolerant of losing a copy. Missense variants: 240 observed, 346.62 expected, observed/expected ratio (o/e) 0.69, 90% interval 0.62 to 0.77. Synonymous variants: 132 observed, 130.19 expected, observed/expected ratio (o/e) 1.01, 90% interval 0.88 to 1.17.
Homologues: Orthologues: chimpanzee RPRD1A (100% identical), dog RPRD1A (100% identical), macaque RPRD1A (99% identical), mouse Rprd1a (99% identical), rat Rprd1a (99% identical), guinea pig RPRD1A (95% identical), tropical clawed frog rprd1a (86% identical), pig RPRD1A (85% identical), rabbit RPRD1A (84% identical), zebrafish rprd1a (73% identical), Drosophila melanogaster CG9018 (47% identical), Caenorhabditis elegans cids-1 (25% identical). Paralogues in human: RPRD1B (69% identical), RPRD2 (31% identical).
Diseases named in the same sentence as RPRD1A in open-access papers:
RPRD1A is named in the same sentence as 6 diseases in open-access papers, as found by Europe PMC text mining. Sharing a sentence is not in itself a finding about the gene and the disease. The quoted sentences say what the papers report.
breast carcinoma (1 paper, 2021). "It has been reported that miR-454-3p promotes breast cancer metastasis through targeting nuclear precursor mRNA domain-containing 1A (RPRD1A), a known tumor suppressor, thereby activating Wnt/β-catenin signaling pathway." (PMID 34017681, 2021).
gastric cancer (1 paper, 2024). A primary or metastatic malignant neoplasm involving the stomach. "Circular RNA Circ0075305 hinders gastric cancer stem cells by indirectly increasing the expression of RPRD1A." (PMID 38714724, 2024). "Moreover, flow cytometry analysis revealed that the knockdown of RPRD1A in gastric cancer cell lines resulted in marked elevated proportion of CD44+ cells." (PMID 38714724, 2024). "Furthermore, a cell fluorescence recovery assay revealed that transfection with Circ-0075305 or miR-708-5p mimic led to changes in the gastric cancer stem cell-related markers CD44 and NANOG; however, these effects were reversed by sh-RPRD1A." (PMID 38714724, 2024).
tumor (4 papers, 2021 to 2024). "This suggests that RPRD1A functions as a tumor suppressor and exerts similar effects on Circ-0075305 in impeding the progression of GC." (PMID 38714724, 2024). "Meanwhile RPRD1A plays a crucial role in tumor stem cell formation, metastasis, and drug resistance." (PMID 38714724, 2024). "Several preliminary studies have already demonstrated RPRD1A acts as a tumor suppressor by competitively binding with β-catenin and inhibiting the formation of TCF4–β-catenin transcription complex." (PMID 38714724, 2024). "Given that RPRD1A overexpressed in HCC and correlated with tumor invasion clinical characteristics, we postulated that RPRD1A would substantially affect the progression of HCC." (PMID 34921137, 2021). "Intriguingly, most cases of HCC showed much higher mRNA levels of RPRD1A than the corresponding para-tumor or normal liver tissues." (PMID 34921137, 2021). "As a result, RPRD1A positively correlated with tumor size, vein invasion, TNM stage and BCLC stage features." (PMID 34921137, 2021). "Consistently, analyses of the TCGA database revealed that HCC tumor tissues had higher mRNA expression of RPRD1A in both paired and unpaired specimens." (PMID 34921137, 2021). "Moreover, MHCCLM3 cells stably expressing shRPRD1A were inoculated into the flanks of nude mice, and the effect of RPRD1A on xenograft tumor growth was evaluated." (PMID 34921137, 2021). "RPRD1A-depletion significantly inhibited tumor growth in vivo compared with control cells." (PMID 34921137, 2021). "The results showed that 78.6% (210/267) para-tumor tissues presented low-expression (score 0 and 1) and 21.4% (57/267) presented high-expression (score 2 and 3) of RPRD1A, while the tumor tissues showed 65.2% (174/267) low-expression and 34.8% (93/267) high-expression (bottom)." (PMID 34921137, 2021). "There seems to be some contradiction between our research and previous reports about the function of RPRD1A in the tumor, indicating the different tumor types may possess different function of specific gene." (PMID 34921137, 2021). "An equal number (1 × 106) of overexpressed Circ-0075305 and RPRD1A knockdown BGC-823 cells were injected subcutaneously into nude mice, and tumor samples were collected after 4 weeks." (PMID 38714724, 2024).
cancer (2 papers, 2021 to 2024). A tumor composed of atypical neoplastic, often pleomorphic cells that invade other tissues. "Together, these data indicated that RPRD1A helped cancer cells resistance to OXP-induced oxidative stress and cell death." (PMID 34921137, 2021). "RPRD1A plays different roles in different cancers, may enhance nuclear translocation of NRF2, thereby inducing the expression of genes that resist oxidative stress, maintain cancer cell survival and promote HCC development." (PMID 38714724, 2024). "Moreover, disturbing the redox homeostasis of cancer cells by genetic knockdown of RPRD1A sensitizes cancer cells to platinum-induced cell death." (PMID 34921137, 2021). "Therefore, RPRD1A enhances the nuclear translocation of NRF2, which induces gene expression for counteracting oxidative stress, maintaining cancer cells survival, and promoting HCC development." (PMID 34921137, 2021).
RPRD1A also shares sentences with these, for which no sentence is quoted: coronary artery disease (1 paper); liver cancer (1).